AR (androgen receptor)
Diseases named in the same sentence as AR in open-access papers (continued):
Sharing a sentence is not in itself a finding about the gene and the disease.
COVID-19 (continued). "Considering the indispensable function of TMPRSS2 in the pathogenicity of SARS-CoV-2, several therapeutics that are effective in attenuating androgen receptor signaling could be repurposed for the treatment of patients with COVID-19." (PMID 34001144, 2021). "In addition to our group, others are testing AR antagonism as a therapeutic strategy for hospitalized patients with COVID-19." (PMID 34225789, 2021). "Accordingly, we hypothesized that therapeutic targeting of androgen receptor signaling will suppress viral infection and thereby ameliorate the severity of symptomatic COVID-19." (PMID 34225789, 2021). "Androgen and androgen receptor (AR) are reported to upregulate ACE2 transcription, which may explain the gender difference in the susceptibility to COVID-19 in terms of mortality and morbidity." (PMID 34305888, 2021). "Taken together, it is plausible that that androgen receptor (AR) may be involved in modulation of the patient’s response to COVID-19 and patients may benefit from antiandrogen treatment." (PMID 33477294, 2021). "If this link proves correct, it could pave the path to novel strategies, including re-purposing of FDA-approved potent androgen synthesis inhibitors or AR antagonists, such as enzalutamide (Enz) and apalutamide, for the treatment of COVID-19." (PMID 34045511, 2021). "Interventional approaches including estrogen-related compounds and androgen receptor antagonists may be considered in patients with COVID-19." (PMID 32646459, 2020). "That expression of TMPRSS2 is dependent on androgen (AR) expression, however, may explain why human males appear to show significantly higher mortality with COVID-19." (PMID 32574196, 2020). "The mechanism-based irreversible action of finasteride and dutasteride led to their successful use as anti-androgen drugs, which may be repurposed for treating COVID-19 patients with excessive androgen receptor signaling 18,19." (PMID 32702725, 2020). "The mechanism-based irreversible action of finasteride and dutasteride has led to their successful use as antiandrogen drugs, which may be repurposed for treating COVID-19 patients with excessive androgen receptor signaling." (PMID 33110062, 2020). "Therefore, androgen-AR-mediated mechanisms could explain sex-specific differences in COVID-19 outcomes by TMPRSS2-independent mechanisms." (PMID 34045511, 2021). "Gender may be considered when analyzing clinical trials in relation to SARS-CoV-2 infection, as gender differences may reveal different approaches that are necessary for the treatment of patients with COVID-19, such as estrogen-related compounds and androgen receptor antagonists." (PMID 33791232, 2021). "Since testosterone/AR signaling is reduced during aging and its reduction is associated with COVID-19 death incidence in men, testosterone therapy may be useful for boosting TMPRSS2/ACE2 signaling, and thereby reducing COVID-19 death incidence." (PMID 34832534, 2021). "Also, sex should be taken into account when designing and analyzing clinical trials of COVID-19, and sex differences may reveal novel therapeutic approaches such as estrogen-related compounds and androgen receptor antagonists." (PMID 32899833, 2020). "LNCaP cells are dependent on AR and express the protein at high levels, so it is possible that AR signaling and subsequent targeting efficacy may be different in the lung epithelial cells of COVID-19 patients." (PMID 33310900, 2020). "Altogether, this evidence suggest that the elevated expression of TMPRSS2 induced by androgens could be one of the explanations for the increased male susceptibility to COVID-19 and the milder disease in children who still do not have high expression of AR." (PMID 33584667, 2020).
COVID-19 (continued). "In addition, the female hormones estrogen and progesterone would boost women’s immunity against severe COVID-19, while, lower expression of the androgen receptor (AR) in women might contribute to reduced vulnerability to complications like acute respiratory distress syndrome." (PMID 38533301, 2024). "Here we characterize the role of ACE2, AR, MX1, ERG, ETV5 and TMPRSS2 for trying a better classification of COVID-19 through knowledge of the disease mechanisms." (PMID 37287057, 2023). "Literature-based data mining and construction of the molecular pathways revealed a total of seven genes connecting ADHD with COVID-19, including CRP, PON1, AR, OXT, IL6, TNFSF12, and IL10.." (PMID 38066446, 2023). "Among these connections, ADHD exerts a promotion effect on COVID-19 through the inhibition of OXT and PON1 and the promotion of CRP, AR, and TNF." (PMID 38066446, 2023). "Here we focus on TMPRSS2, and related genes ACE2, MX1, AR, ETV5 and ERG, by its own or combined with clinical data, as an easy and relevant classifier of COVID-19 aggressiveness." (PMID 37287057, 2023). "Our main aim is to try a molecular characterization in these main related genes (TMPRSS2, AR, ACE2 and MX1) to better understand COVID-19 severity; and trying to initiate the lines for molecular biomarkers in COVID-19 management." (PMID 37287057, 2023). "Further bioinformatic analysis revealed 8 core targets (EGFR, AR, ESR1, MAPK8, MDM2, EZH2, ERBB2 and MAPT) in the VitD-COVID-19-osteoporosis network." (PMID 36307516, 2022). "The potential mechanism of action of HXZQ for COVID-19 is inhibiting SARS-CoV-2 replication, improving immune, and anti-inflammatory, mainly by acting on 3CLpro, PTGS2, AR, HSP90AB1, CAMSAP2, PPARG, NOS2, and other targets." (PMID 36388945, 2022). "We postulated that the GR and AR modulator, PT150, would reduce infectivity of SARS-CoV-2 and prevent inflammatory lung injury in the Syrian golden hamster model of COVID-19 by down-regulating expression of critical genes regulated through these receptors." (PMID 35250984, 2022). "Evidence suggests that androgen receptor (AR), angiotensin-converting enzyme 2 (ACE2) and transmembrane serine protease 2 contribute to the pathophysiology of COVID-19." (PMID 34306167, 2021). "Mechanistically, the clinical relevance of COVID-19 to cancer is based on cytokine, IFN-I, androgen receptor (AR), and immune checkpoint signaling." (PMID 34001144, 2021). "By implications from the ongoing clinical trial with an AR antagonist for preventing COVID-19 infection, our studies suggest that WBM is a potential dietary intervention to prevent COVID-19 entry into the cells of the lungs, small intestine, and kidneys." (PMID 34341347, 2021). "The clinical trial using AR antagonists, proxalutamide/GT0918, in COVID-19 is currently underway (ClinicalTrials.gov, NCT04446429." (PMID 34341347, 2021). "In addition, variation in the androgen receptor gene may predict COVID-19 disease severity." (PMID 33643746, 2021). "Furthermore, since the androgen receptor (AR) gene is also located on the X chromosome, the sensitivity to hormones such as testosterone could represent an important determinant factor for the severity of COVID-19 in men." (PMID 33584667, 2020). "Some of these studies are examining the efficacy of the AR antagonists enzalutamide (NCT04456049, NCT04475601) or bicalutamide (NCT04509999, NCT04374279) in COVID-19 patients." (PMID 33310900, 2020). "Critically, these therapies led to decreased SARS-CoV-2 infection in cellular models, and, thus, these findings support further studies into AR and BET inhibitors as candidate treatment modalities for COVID-19." (PMID 33310900, 2020). "Proxalutamide as a novel potent AR antagonist has been shown to downregulate the expression of ACE2 and TMPRSS2 in lung cancer cells, and also accelerate viral clearance in mild to moderate patients with COVID-19." (PMID 37322522, 2023).
COVID-19 (continued). "Pathway analysis identified several immunity-related genes that may link ADHD to COVID-19, including CRP, OXT, IL6, PON1, AR, TNFSF12, and IL10." (PMID 38066446, 2023). "Reduced androgenic signaling predisposes men to a more severe form: low testosterone levels and reduced androgen receptor activity (CAG > 23) expose the host to an excessive inflammatory response, leading downstream to the multi-organ damage seen in severe COVID-19." (PMID 36101355, 2022). "This would correlate well with our IHC, showing that in most COVID-19 testis the AR level is absent/reduced." (PMID 35453608, 2022). "In this review, we highlight the clinical and molecular similarities between cancer and COVID-19 and summarize the four major signaling pathways at the intersection of COVID-19 and cancer, namely, cytokine, type I interferon (IFN-I), androgen receptor (AR), and immune checkpoint signaling." (PMID 34001144, 2021). "Considering that the activated androgen receptor regulates transcription of TMPRSS2 gene, androgen hormone receptors signaling antagonists could be explored as treatment strategies against COVID-19 for their role in downregulating TMPRSS2." (PMID 34391321, 2021). "Since AR controls the transcription of TMPRSS2, this may serve as a potential targeted therapy to reduce the severity of COVID-19 in male patients." (PMID 33364247, 2020). "However, some randomized, controlled clinical trials of AR inhibition in COVID-19 patients have not produced encouraging results." (PMID 37459541, 2023). "In the presence of a less active androgen receptor, the immunosuppressive effects of testosterone are not fully mediated, exposing the body to the cytokine storm responsible for the multi-organ damage seen in COVID-19." (PMID 36101355, 2022). "The testicular tissues from COVID-19 negative patients, inflammatory changes or previous intensive care controls were positive for the AR protein (indicated by the brown nuclei (black arrowheads) albeit diminished in F and H. Samples from a patients with COVID-19 were negative for AR." (PMID 35453608, 2022). "Enzalutamide, a potent inhibitor of the androgen receptor (AR), may have antiviral activity in the prostate glands of male COVID-19 patients but has no therapeutic effect in patients with a COVID-19 lung infection." (PMID 36078166, 2022). "Reduced androgenic signaling could predispose men to a more severe form: low testosterone levels and a reduced androgen receptor activity (CAG > 23) expose the host to an excessive inflammatory response, leading downstream to the multi-organ damage seen in severe COVID-19." (PMID 36101355, 2022). "Similarly, the addition of androgen receptor–directed therapy within 30 days of COVID-19 diagnosis to ADT vs ADT alone did not statistically significantly affect overall survival (androgen receptor–directed therapy: HR = 1.27, 95% CI = 0.69 to 2.32, P = .44)." (PMID 35657341, 2022). "In terms of ER ligands, on the basis that agonists inhibit TMPRSS2 expression it would be ER agonists rather than, as is the case for AR, antagonists that may be useful in COVID-19." (PMID 34328182, 2021). "Accordingly, the reduction of the TMPRSS2 expression by blocking the androgen receptor would decrease SARS-CoV-2 entry into human cells, which is corroborated by studies showing protection from more severe states related to COVID-19 with the use of antiandrogens." (PMID 33643746, 2021). "Whether or not AR antagonism should be considered as a therapeutic strategy for patients hospitalized with COVID-19 will depend on the results of this and related trials." (PMID 34225789, 2021). "Therefore, given the involvement of AR in SARS-CoV-2 pathogenesis, these compounds may have some preventative potential against COVID-19." (PMID 33364247, 2020).
COVID-19 (continued). "In addition, previous studies have pointed out that the androgen receptor (AR) signal controls the expression of TMPRSS2, and TMPRSS2 is necessary for the SARS-CoV-2 spike protein to infect the human body, so androgen receptor inhibitors are used and have therapeutic potential for COVID-19." (PMID 35057070, 2022). "Moreover, our findings on cardiac and renal AR and SARS-CoV-2 viral entry proteins regulation indicate possible molecular mechanisms by which excess androgens and HFD interact and may lead to increased cardiorenal COVID-19 severity in PCOS." (PMID 34575910, 2021). "Specially, the targets of the novel CPI such as AR, VDR, CTSL and Cathepsin B (CTSB) have been reported to be relevant for the treatment of COVID-19, thus these new predicted CPIs that have not been verified are good candidates for wet experiment exploration." (PMID 35275993, 2022). "Therefore, AR inhibitors like nonsteroidal antiandrogen (enzalutamide, bicalutamide, apalutamide, and darolutamide, steroidogenesis inhibitors, 5-alpha reductase inhibitors, and chemical castration with gonadotropin-releasing hormone analogs could be valid treatment in the COVID-19 patients." (PMID 35399920, 2022). "Thus, in cell types where AR regulation of ACE2 and TMPRSS2 does not exist, the broader transcriptional repression by BET inhibitors may block expression of these key host factors, and agents targeting BET proteins may have a different therapeutic efficacy in COVID-19 than direct AR inhibitors." (PMID 33310900, 2020).
lung carcinoma (78 papers, 2005 to 2025). "The results demonstrated that loss of AR promoted lung cancer metastasis, however, when shcirc-SLCO1B7 was introduced in combination with shAR, it effectively blocked shAR-mediated lung cancer metastasis." (PMID 37564195, 2023). "Overall, these findings provide insight into the molecular mechanisms underlying the suppressive role of AR in lung cancer cell progression." (PMID 37564195, 2023). "Our study aligns with these finding by demonstrating that the loss of androgen receptor (AR) promotes lung cancer cell invasion and decreases drug response." (PMID 37564195, 2023). "AR is associated with the development of lung cancer, and AR abnormal expression often leads to poor prognosis and affects the survival of patients with lung cancer." (PMID 32929340, 2020). "Mutation detection of DNA extracted from CTC-enriched samples demonstrated activating mutations in the EGFR, KRAS, and AR genes in patients suffering from lung cancer, colorectal cancer (CRC), and castration-resistant prostate cancer (CRPC) respectively." (PMID 26980749, 2016). "The AR signaling pathways play critical roles in the development and progression of PCa, a leading cause of cancer death second to lung cancer in men." (PMID 24397471, 2014). "The differential expression and activation of AR in response to environmental pollutants, the inflammatory microenvironment, and AR gene mutations could contribute to the observed gender disparities in lung cancer incidence and progression." (PMID 39725665, 2024). "By reducing TPD52 expression, the androgen receptor inhibits the invasion of lung cancer and boosts the cisplatin response." (PMID 39757112, 2025). "Conversely, the effects of testosterone and androgen receptor (AR) in lung cancer are still unclear." (PMID 40612952, 2025). "In lung cancer, AR influences proliferation and therapy sensitivity through interactions with EGFR and MAPK/ERK pathways, with effects varying by tumor subtype and AR splice variant expression." (PMID 41614805, 2025). "For example, AR promotes metastasis in lung cancer by modulating the miR-23a-3p/EPHB2 signaling axis." (PMID 41228208, 2025). "Although the role of AR in lung cancer remains controversial, some studies have shown that it promotes cell proliferation, migration and invasion." (PMID 40612952, 2025). "While most of the discussion on sex hormones and lung cancer has been focused on the role of estrogen, several studies reported the presence of androgen receptor in the lung and its role in promoting lung cancer development." (PMID 39396092, 2024). "Detailed mechanisms have been identified in prostate, breast, and lung cancer, such as AR dimerization, ERα stabilization, and NF-κB activation, respectively." (PMID 38803221, 2024). "We used network pharmacology, computer molecular docking, and bioinformatics technology to study the effective ingredients and mechanism of Yi Fei Qing Hua Granules (YQG) inhibited lung cancer AR expression and proliferation." (PMID 37716981, 2023). "Overall, AR plays an important role in suppressing lung cancer progression by altering the circ-SLCO1B7/TPD52 signaling axis." (PMID 37564195, 2023). "Conversely, AR reduction, achieved by introducing AR-shRNA (shAR), resulted in a significant addition in lung cancer cell invasion and decreased cisplatin response of H1299 and A549 cells." (PMID 37564195, 2023). "The androgen receptor, which is expressed mostly in pneumocytes and lung epithelium of male patients, is known to be an active player in lung cancer pathogenesis." (PMID 38660429, 2023). "According to the analysis of TCGA database, AR mRNA level was found to be decreased in lung cancer tumor tissues as compared to the normal tissues." (PMID 37564195, 2023). "Taken together, these findings support the notion that AR functions as a tumor suppressor of lung cancer progression through the regulation of circ-SLCO1B7." (PMID 37564195, 2023).